IL4 (interleukin 4)
Diseases named in the same sentence as IL4 in open-access papers (continued):
Sharing a sentence is not in itself a finding about the gene and the disease.
epilepsy (17 papers, 2014 to 2025). A brain disorder characterized by episodes of abnormally increased neuronal discharge resulting in transient episodes of sensory or motor neurological dysfunction, or psychic dysfunction. "A similar association between CD200R mRNA expression and IL-4 levels was demonstrated in children with different forms of epilepsy." (PMID 33804413, 2021). "However, whether IL-4 has protective effects on reactive astrocyte hyperplasia and inflammation caused by epilepsy needs further verification." (PMID 33013320, 2020). "IL-4 therefore likely plays a significant role in epileptogenesis and the physiopathology of epilepsy." (PMID 36614274, 2023). "IFN-γ can reduce the proportion of M2 microglia and the expression of IL-4 and IL-10 after epilepsy." (PMID 34594188, 2021). "Several researchers have shown that the concentration of IL-4, IL-8 and IL-17 can correlate with the frequency and severity of seizures, suggesting a key role for cytokines in the diagnosis and treatment of epilepsy." (PMID 34069567, 2021). "Otherwise, low levels of IL-4 in epileptic patients have been shown to decrease inflammation-related epilepsy." (PMID 34202937, 2021). "For example, increased concentrations of serum IL-1b, IL-1Ra, IL-2, IL-4, IL-6, IL-8, IFNy and IL-17 have been observed in patients with epilepsy, as well as increased levels of IL-6 and IL-17 in the cerebrospinal fluid." (PMID 34069567, 2021). "This work found that, compared to controls, the level of IL4-590/C allele and TCC haplotype was higher and the frequencies of GCC, TTT, TTC haplotypes, and that the IL-4 (-590) TC, IL-4 (-33) TC genotypes were lower in epilepsy patients." (PMID 33013320, 2020). "This review article focuses on the regulatory role of IL-4 in the pathological changes of glial cells related to epilepsy." (PMID 33013320, 2020). "In adult human microglia from epilepsy patients, most cells expressed a KCa3.1 current, which was unaffected by LPS and slightly increased by IL-4." (PMID 29780305, 2018). "For epilepsy and bipolar disorder, overlapping results regarding the cytokine system have been reported, namely, alterations of IL-1β, IL-2, IL-4, IL-6, and TNF-α." (PMID 24757498, 2014). "Anti-inflammatory cytokines such as IL-10 and IL-4 are key players in mitigating the detrimental effects of neuroinflammation and may offer therapeutic avenues for preventing or ameliorating epilepsy." (PMID 40723787, 2025). "IL-4 treatment can also regulate microglia activation, reduce the release of pro-inflammatory cytokines, and improve the long-term harmful effects of seizures in the pilocarpine-induced epilepsy model." (PMID 34594188, 2021). "Similarly, in the serum of 22 out of 100 patients with epilepsy, IL-4 was significantly increased within 24 h of seizures." (PMID 33013320, 2020). "Consequently, IL-4 very likely plays an important role in the development of epilepsy by regulating neuron-glial interactions." (PMID 33013320, 2020). "Currently, many studies are focusing on the relationship between IL-4 and epilepsy." (PMID 33013320, 2020). "We additionally propose that IL-4 may play a protective role in epileptogenesis and suggest that IL-4 may be a novel therapeutic target for the treatment of epilepsy." (PMID 33013320, 2020). "Therefore, they concluded that the association of IL-4 polymorphisms with FS and epilepsy of children does not exist." (PMID 33013320, 2020). "Thus, IL-4 likely plays an important role in epileptogenesis and the physiopathology of epilepsy." (PMID 33013320, 2020). "We propose the Inflammatory Drug-Resistant Epilepsy Index (IDREI), a novel biomarker derived from plasma concentrations of ICAM-1, IL-4, and IL-10 and CSF levels of NfL, for the prediction of DRE." (PMID 40723787, 2025). "It has been reported that intraperitoneal injection of IL-4/ interferon (IFN)-γ modulated the proportions of microglial phenotypes and improved epilepsy outcomes in a pilocarpine model of acquired epilepsy." (PMID 32206297, 2020).
epilepsy (continued). "Compared with children with non-inflammatory neurological diseases like epilepsy, IL-4 was found to be increased in patients with acute and persistent SC and Il-10 and IL-12 were only elevated in patients with acute SC." (PMID 36061386, 2022). "Interestingly, another group very recently patch‐clamped adult human microglia from neocortical tissue surgically removed from epilepsy patients and found high KCa3.1 current densities (∼580 per cell), which, similar to our observations here, did not significantly change with LPS or IL‐4 treatment." (PMID 27696527, 2017).
vitiligo (17 papers, 2012 to 2025). Generalized well circumscribed patches of leukoderma that are generally distributed over symmetric body locations and is due to autoimmune destruction of melanocytes. "IL-4 is a Th2-associated cytokine, which is reduced in vitiligo patients, contributing to Th1/Th2 imbalance." (PMID 40725033, 2025). "We found that IL-4 (OR 2.72, 95%CI 1.19–6.22, p = 0.018) has an increased risk of developing vitiligo." (PMID 38695020, 2024). "PSMB8 polymorphism in addition to previously reported susceptibility loci such TNFA, TNFB, IL1B, IFNG, NALP1, IL4 etc. demonstrate immunogenetic predisposition in vitiligo patients from Gujarat." (PMID 28700671, 2017). "IL-4 is a suggestive indicator of vitiligo risk (OR = 2.948, 95% CI = 1.28–6.79, p = 0.011)." (PMID 38357652, 2024). "According to the results of the MR analysis, there were causal links between IL-4 and vitiligo." (PMID 38695020, 2024). "Our research reveals that a genetically determined increased level of circulating IL-4 may be linked to a higher risk of developing vitiligo." (PMID 38695020, 2024). "First, higher genetically predicted levels of IL-4 were associated with a higher risk of vitiligo." (PMID 38357652, 2024). "LEF administration demonstrated significant immunomodulatory capacity, reducing the serum levels of Th1-associated pro-inflammatory cytokines (IFN-γ, TNF-α, IL-2) while upregulating Th2-derived anti-inflammatory mediators (IL-4, IL-10) in vitiligo mice." (PMID 40725033, 2025). "When AU, vitiligo, and combinations of the two are comorbid with AD, there is an expectation of circulating IL-4/13 elevations and localized IL-4/13 elevation that support a potential role for dupilumab therapy in these conditions." (PMID 40933636, 2025). "This shows the reasonability and scientificity of IL-4 inhibition in treating some vitiligo patients." (PMID 38695020, 2024). "We observed that rising IL-4 levels generated an enhanced probability of vitiligo in IVW (OR 2.72, 95%CI 1.19–6.22, p = 0.018)." (PMID 38695020, 2024). "When conventional treatments are ineffective, patients with vitiligo can receive therapies such as JAK1/3 inhibitors or an IL-4 monoclonal antibody inhibitor to manage their condition." (PMID 38695020, 2024). "Understanding how IL-4 behaves and works differently during the vitiligo process is crucial to effectively deploying IL-4 antagonists as a novel therapeutic approach." (PMID 38695020, 2024). "The development of innovative treatment approaches (such as tofacitinib or dupilumab) that focus on blocking IL-4 as a novel way of preventing and treating vitiligo is significantly impacted by our findings." (PMID 38695020, 2024). "More significantly, given the inherent limits of MR studies, it would be desirable to investigate the connection between blood levels of IL-4 and the severity of vitiligo in a large group of vitiligo patients in the future to validate the previous findings." (PMID 38695020, 2024). "We discovered an affinity between raised IL-4 levels and a higher chance of developing vitiligo (OR 2.72, 95%CI 1.19–6.22, p = 0.018)." (PMID 38695020, 2024). "According to the research, JAK3 and the cytokines IL-4 have a significant role in the etiology of vitiligo." (PMID 38695020, 2024). "A comprehensive understanding of the function and regulatory mechanisms of IL-4 can help unravel the pathophysiological mechanisms of vitiligo and provide new targets and strategies for its treatment and intervention." (PMID 38357652, 2024). "Levels of IL-4 can be both elevated and lowered throughout the pathogenesis of vitiligo, according to a significant number of studies." (PMID 38695020, 2024). "Furthermore, IL-4 may contribute to the risk of developing vitiligo." (PMID 38357652, 2024). "Candidate gene studies highlight the role of autoimmunity in vitiligo, as polymorphisms in IL1B, IL4, PSMB8, NLRP1, NPY, FOXP3, and IFNG genes were found to be associated with vitiligo." (PMID 36164321, 2022).
vitiligo (continued). "The function of IL-4 in the vitiligo progression is still ambiguous, nevertheless." (PMID 38695020, 2024). "Elevated levels of IL-4 may affect the activation status of immune cells, leading to increased attack on melanocytes and further promoting the development of vitiligo." (PMID 38357652, 2024). "Thus, one of the possible mechanisms by which IL-4 plays a significant and vital role in vitiligo is the stimulation of the necrosis of melanocytes." (PMID 38695020, 2024). "The JAK1/JAK3 inhibitor tofacitinib abrogates IL-4 signaling and the differentiation of Th2 cells; moreover, tofacitinib is an effective and well-tolerated therapy option for people with refractory vitiligo, according to numerous research." (PMID 38695020, 2024). "Some IL-4 findings in vitiligo studies seem to be contrary to ours." (PMID 38357652, 2024). "Thus, the significance of Th2 cells and the cytokines IL-4 in the development of vitiligo sparks researchers’ attention." (PMID 38695020, 2024). "We confirmed the drastic elevation of IL-4 in vitiligo mouse skin compared with the control." (PMID 36672151, 2023). "It is hypothesized that skewed balance to Th1 is directly responsible for vitiligo development by changing IFN-γ/IL-4, Tbet/Gata3 profiles in vitiligo patients compared to controls." (PMID 33921371, 2021). "Upon stimulation with interleukin-4 (IL-4), B cells undergo proliferation and regulate immunoglobulin class switching (such as IgG1 and IgE), thereby facilitating T-cell development, which may contribute to the pathogenesis of vitiligo." (PMID 41438750, 2025). "The reverse MR data analysis showed that vitiligo had no causal effect on IL-4." (PMID 38695020, 2024). "The scatter plots revealed that IL-4 may have a detrimental influence on vitiligo protection." (PMID 38695020, 2024). "This suggests that IL-4 may contribute to the pathogenesis of vitiligo." (PMID 38357652, 2024). "Hence, tofacitinib, a JAK3 inhibitor designed to lower IL-4-related Th2 cytokines, may thus be useful in treating certain cases of refractory vitiligo." (PMID 38695020, 2024). "In addition, a variety of cytokines secreted by T helper cell subsets- Th1 (IFN-γ, TNF-α, IL-2) and Th2 (IL-4, IL-10, IL-13) not only exacerbate autoimmune responses but also perpetuate the vicious cycle of immune dysfunction, ultimately leading to the clinical manifestations of vitiligo." (PMID 40725033, 2025). "Concurrently, the cytokine profile shift—characterized by reduced IFN-γ, TNF-α, and IL-2, alongside elevated IL-4 and IL-10—suggests that LEF promotes an anti-inflammatory milieu, countering the Th1 axis that drives vitiligo." (PMID 40725033, 2025). "Nouri-Koupae’s study revealed that in patients with vitiligo compared with controls, mRNA expression was significantly higher for IFN-γ and significantly lower for IL-4 mRNAs." (PMID 38695020, 2024). "Furthermore, vitiligo is defined by the presence of an altered immunological balance, which is predominantly seen in an imbalance between the cytokines expressed by Treg/Th2 lymphocyte subsets (IL-4) and Th1/Th17 lymphocyte subsets (TNF-α, IFN-γ, IL-17, and IL-8)." (PMID 38695020, 2024). "Meanwhile, there is mounting evidence that the immunological milieu of vitiligo is also characterized by cytokines connected to other Th2 cell responses, such as IL-4, IL-5, IL-10, IL-13, and IL-31, rather than just Th1 cells and related cytokines (IFN-γ, TNF-α, and IL-2)." (PMID 38695020, 2024). "Furthermore, inflammatory factors and interleukin (IL) signaling pathway (IL4 and IL10), adaptive immune response (IFNG), and cell apoptosis (FASLG and TNF) also played critical roles in the clarification of the mechanisms of KBL on vitiligo." (PMID 31781265, 2019).
AIDS (16 papers, 2009 to 2025). A syndrome resulting from the acquired deficiency of cellular immunity caused by the human immunodeficiency virus (HIV). "It has been reported that acquired immune deficiency syndrome patients with decreased levels of DHEA-S show excessive cytokine production by Th2 cells (IL-4, IL-5, IL-6, and IL-10) and suppression of other cytokines (IL-2, IFN-γ, IL-12)." (PMID 29694639, 2018). "Although high production of IFN-γ is associated with slower progression to AIDS, IL-4 production is reportedly higher in individuals with rapid progression to AIDS, indicating that the Th1/Th2 balance is essential for determining the course of viral infection." (PMID 32711474, 2020). "The absence/reduction of serum pro-inflammatory cytokines such as TNFα, G-CSF, GM-CSF and VEGF (vascular-endothelial growth factor), and increase in serum IL-17 and IL-4, predispose AIDS patient with CM to developing subsequent CM-IRIS." (PMID 29333430, 2017). "In contrast, high CSF IL-4 levels have been associated with a protective immune response in AIDS-CM patients from South Africa." (PMID 29333430, 2017). "Recently, haplotypes of the IL-4 and IL-10 genes associated with AIDS progression have been reported." (PMID 20380696, 2010). "Th2 cells produce cytokines like interleukin-4 (IL-4) and interleukin-10 (IL-10), which have anti-inflammatory properties but can lead to systemic AIDs when overactivated." (PMID 40677716, 2025). "Clerici and Shearer observed that the progression of HIV infection in AIDS is characterized by the loss of IL-2 and IFN-γ production and the increase in IL-4 and IL-10." (PMID 39062756, 2024). "IL-4 synthesis is stimulated during the development of AIDS as a result of HIV-induced domination of Th2 cell stimulation." (PMID 35632739, 2022). "On the other hand, the Th2-specific cytokines, i.e., IL-4, IL-5, IL-6, IL-10, and IL-13, are associated with disease progression and lead to the progression of HIV infection to AIDS." (PMID 31641392, 2019). "This may result in the low production of IL-4 observed in our study and an acceleration of the disease towards the AIDS phase." (PMID 38643073, 2024). "Patient-derived AIDS-KS cells can produce IL-4 and express surface IL-4R." (PMID 30619193, 2018). "At the same time, the secretion of cytokines such as IFN-α, IL-2, IL-4, IFN-γ, and TNF-α, are beneficial to delay the disease progression of AIDS." (PMID 35211115, 2022). "Thus, IL-4 could be an important factor in viral evolution and AIDS pathogenesis." (PMID 35632739, 2022). "A study indicated that high serum pre-ART levels of IL-4 and IL-17 were predictive of future immune reconstitution inflammatory syndrome (IRIS) in AIDS patients with CM." (PMID 34051748, 2021). "Similarly, high levels of serum IL-4 correlated with development of IRIS and subsequent death in AIDS-CM patients from Brazil and Uganda." (PMID 29333430, 2017). "In HIV-infected patients, the amount of IL-10, but not IL-4, increases significantly in patients with AIDS." (PMID 20380696, 2010). "This lack of IL-4 may occur due to the immune response to cryptococcus of AIDS patients with CM." (PMID 34051748, 2021). "The maximum frequency of CD4+ T cells expressing IL-4 was seen in HIV-infected individuals without AIDS, whereas the rate of IL-10-producing CD4+ T cells was highest in patients with AIDS." (PMID 39062756, 2024). "High numbers of CD8+ T cells (Tc2) producing IL-4, but not IFN-γ, have been found in AIDS patients." (PMID 19402893, 2009).
bronchiolitis (16 papers, 2009 to 2025). Inflammation of the bronchioles characterized by swelling of the bronchioles and mucus accumulation. "Along these lines, acute bronchiolitis caused by RSV infection is known to activate Th2 cell–related cytokines such as IL–4 and IL–5, resulting in an imbalanced immune response leading to airway mucus overproduction." (PMID 35603159, 2022). "However, data from human metapneumovirus-positive infants with bronchiolitis showed that low IFN-γ/IL4 ratio in nasopharyngeal samples was associated with short-lasting post-viral wheeze." (PMID 34925333, 2021). "Moreover, the authors found an association of the hRSV disease severity and the IL-4 locus in children older than 6 months that were hospitalized by hRSV bronchiolitis." (PMID 30936869, 2019). "It should be noted that certain polymorphism, such as IL-4 590T and IL-4Ralpha R551 alleles, could be linked to more sereve bronchiolitis and the IL-13 Gln allele may identify children at risk for persistent wheezing as shown in RSV affected children." (PMID 19781072, 2009). "A higher IL-4/IFN-γ ratio in nasal lavage fluid was detected in RSV-infected infants with acute bronchiolitis than in their counterparts with only RSV-related upper respiratory tract infection alone." (PMID 36861979, 2023). "Acute bronchiolitis elicited increased levels of IL-4 and IL-10 but decreased level of IFN-γ and IL-2." (PMID 34395633, 2021). "Genetic polymorphisms of SFTPA (surfactant protein A), SFTPD (surfactant protein D), TLR (toll like receptor) 4, TNF (tumor necrosis factor), IL4 (interleukin 4), IL9, IL10, IL8, IL13, IL4RA, and CCL5 have been reportedly associated with a susceptibility to RSV-induced bronchiolitis." (PMID 23986756, 2013). "RSV infections can induce a change of the Th1/Th2 balance, expressed by an increase of the IL-4/IFN-gamma ratio and a persistent IgE response over the years, and human rhinovirus-induced bronchiolitis carries a markedly risk of persistent wheezing and childhood asthma." (PMID 22439773, 2012). "In our study, we demonstrated that the levels of IL-33 and Th2-related cytokines IL-4 and IL-10 in RSV infected acute bronchiolitis in serum of infants were significantly increased." (PMID 34395633, 2021). "It was reported that the production of Th2 cytokines IL-4 and IL-10 was promoted by IL-33, and Th2 immune response was described to influence the pathogenesis of respiratory syncytial virus (RSV) acute bronchiolitis." (PMID 34395633, 2021). "We used ELISA to detect IL-4, IL-5, TNF-α, and IgE in the serum of children in both groups, and the results suggested that IL-4, IL-5, TNF-α, and IgE were significantly elevated in children with bronchiolitis compared with healthy children." (PMID 37389334, 2023). "Severe/hypoxic bronchiolitis exhibited a higher level of IL-4 (a Th2 marker) than that of a group with nonhypoxic bronchiolitis." (PMID 36861979, 2023).